RNF14 (ring finger protein 14)
Description:
E3 ubiquitin-protein ligase that plays a key role in the RNF14-RNF25 translation quality control pathway, a pathway that takes place when a ribosome has stalled during translation, and which promotes ubiquitination and degradation of translation factors on stalled ribosomes. Recruited to stalled ribosomes by the ribosome collision sensor GCN1 and mediates 'Lys-6'-linked ubiquitination of target proteins, leading to their degradation. Mediates ubiquitination of EEF1A1/eEF1A and ETF1/eRF1 translation factors on stalled ribosomes, leading to their degradation. Also catalyzes ubiquitination of ribosomal proteins RPL0, RPL1, RPL12, RPS13 and RPS17. Specifically required to resolve RNA-protein cross-links caused by reactive aldehydes, which trigger translation stress by stalling ribosomes: acts by catalying 'Lys-6'-linked ubiquitination of RNA-protein cross-links, leading to their removal by the ATP-dependent unfoldase VCP and subsequent degradation by the proteasome. Independently of its function in the response to stalled ribosomes, acts as a regulator of transcription in Wnt signaling via its interaction with TCF transcription factors (TCF7/TCF1, TCF7L1/TCF3 and TCF7L2/TCF4). May also play a role as a coactivator for androgen- and, to a lesser extent, progesterone-dependent transcription.
Synonyms: ARA54; HRIHFB2038; HFB30; TRIAD2
Tractability: PROTAC: UniProt records ubiquitination sites on it; ubiquitination databases record sites on it; its protein half-life has been measured.
Gene: Protein-coding gene on chromosome 5 (141,958,328 to 141,990,292, forward strand). Ensembl gene ENSG00000013561.
Subcellular location: Cytoplasm; Nucleus
Subcellular location (Human Protein Atlas): Nucleoplasm; Cytosol
Pathways (Reactome):
Immune System: Antigen processing: Ubiquitination & Proteasome degradation
Gene Ontology:
Molecular function: nuclear androgen receptor binding; protein binding; ubiquitin protein ligase activity; ubiquitin-like protein transferase activity; transcription coactivator activity; ubiquitin conjugating enzyme binding; ubiquitin-protein transferase activity; zinc ion binding
Biological process: positive regulation of DNA-templated transcription; protein K6-linked ubiquitination; protein ubiquitination; protein-RNA covalent cross-linking repair; regulation of androgen receptor signaling pathway; regulation of canonical Wnt signaling pathway; regulation of DNA-templated transcription; rescue of stalled ribosome; ubiquitin-dependent protein catabolic process; androgen receptor signaling pathway; regulation of transcription by RNA polymerase II; signal transduction
Cellular component: cytoplasm; cytosol; cytosolic ribosome; nucleoplasm; nucleus; ubiquitin ligase complex
Genetic constraint (gnomAD): Loss-of-function variants: 25 observed, 54.01 expected, observed/expected ratio (o/e) 0.46, 90% interval 0.34 to 0.65. The upper end of that interval is the gene's LOEUF score, 0.65, which puts it in group 2 of 6, group 1 being the genes least tolerant of losing a copy. Missense variants: 400 observed, 581.95 expected, observed/expected ratio (o/e) 0.69, 90% interval 0.63 to 0.75. Synonymous variants: 194 observed, 212.24 expected, observed/expected ratio (o/e) 0.91, 90% interval 0.81 to 1.03.
Homologues: Orthologues: chimpanzee RNF14 (99% identical), macaque RNF14 (99% identical), dog RNF14 (96% identical), rabbit RNF14 (95% identical), pig RNF14 (94% identical), rat Rnf14 (92% identical), guinea pig RNF14 (91% identical), mouse Rnf14 (91% identical), tropical clawed frog rnf14.2 (57% identical), zebrafish rnf14 (55% identical), zebrafish RNF14 (43% identical), Caenorhabditis elegans F56D2.2 (31% identical), and 2 more. Paralogues in human: ANKIB1 (20% identical), PRKN (17% identical), RNF19A (16% identical), RNF19B (16% identical), ARIH2 (16% identical), ARIH1 (15% identical), RNF217 (15% identical), RNF144A (13% identical), RNF144B (13% identical).
Diseases named in the same sentence as RNF14 in open-access papers:
RNF14 is named in the same sentence as 9 diseases in open-access papers, as found by Europe PMC text mining. Sharing a sentence is not in itself a finding about the gene and the disease. The quoted sentences say what the papers report.
breast carcinoma (1 paper, 2009). "In our study there are 12 nonBRCA1-mutant samples which exhibit the relation RNF14 <TMEM57 <PPP1CB, of which 7 are "basal-like" tumors, a subtype of breast cancer associated with lack of expression of the estrogen receptor and poor prognosis." (PMID 19695104, 2009). "Although no direct links exist between RNF14 and BRCA1, our PPI analysis shows that indirect interactions occur, and they involve important proteins in breast cancer biology, like the estrogen and androgen receptors." (PMID 19695104, 2009).
inflammatory bowel disease (1 paper, 2024). A spectrum of small and large bowel inflammatory diseases of unknown etiology. "From the DMR analysis, TRIM40 has recently been associated with inflammation in the context of inflammatory bowel disease, RNF14 regulates mitochondrial and immune-related functioning, and HIVEP3 regulates the development of innate-like T cells." (PMID 38296944, 2024).
memory impairment (1 paper, 2020). "Specifically, CKD‐504 increased acetylation of several chaperones and E3 ligases as well as tau itself, resulting in recruitment of the novel tau targeting E3 ligases such as UBE2O and RNF14 to tau, which lead to the rescue of synaptic pathology and memory impairment in ADLPAPT mice." (PMID 31763743, 2020).
cancer (3 papers, 2021 to 2025). A tumor composed of atypical neoplastic, often pleomorphic cells that invade other tissues. "CHIP was highly expressed in most cancer types, and MDM2, RNF14, and RNF4 were expressed in most tumors." (PMID 41194439, 2025). "Previous studies have reported that RNF14, RNF31, RNF144B, RNF216 and ARIH1 mainly play carcinogenic roles, while ARIH2 and PARK2 generally play anticancer roles in malignant tumors." (PMID 35732617, 2022).
tumor (2 papers, 2025 to 2026). "This analysis revealed associations with multiple proteins, including SMAD3, RNF14, PPM1A, and OPHN1, implicating PCDH1 in signaling cascades relevant to tumor progression and stemness regulation." (PMID 41602375, 2026). "Ring Finger Protein 14 (RNF14) is an E3 ubiquitin ligase involved in protein degradation and signaling regulation in CRC, RNF14 overexpression is associated with poor prognosis and contributes to tumor growth by modulating key oncogenic pathways, such as Wnt/β-catenin signaling." (PMID 41331125, 2025).
infection (1 paper, 2021). The state of being infected such as from the introduction of a foreign agent such as serum, vaccine, antigenic substance or organism. "The average effect of each 1 μg/m3 increase in DC in the prior 7 days, regardless of infection type, is a log2-fold increase of 3.5 for RNF14 and 2.4 for UBE2F, two genes participating in antigen presenting cell pathways." (PMID 34593881, 2021).
RNF14 also shares sentences with these, for which no sentence is quoted: prostate carcinoma (3 papers); colon cancer (1); epilepsy (1).